INS (insulin)
Diseases named in the same sentence as INS in open-access papers (continued):
Sharing a sentence is not in itself a finding about the gene and the disease.
Insulin resistance (continued). "Moreover, the analysis of serum insulin levels to confirm insulin resistance was beyond the scope of the study." (PMID 35677010, 2022). "In a previous study, scientists demonstrated that M1 macrophages could aggravate insulin resistance, and CD11c+ cell depletion led to decreased adipose tissue inflammation and rapid normalization of insulin sensitivity." (PMID 35757707, 2022). "However, significant difference was noted between patients with HCC and patients with liver cirrhosis regarding serum insulin, presence of insulin resistance and liver function ALT, AST, GGT, AFP, serum albumin, GLR, TAG/HDL-C, and LAIR-1 expression." (PMID 36293412, 2022). "Early in pregnancy, there is a progressive increase in maternal insulin secretion to compensate for the physiological changes in insulin sensitivity, which is proposed to increase the risk of developing GDM in women with pre-existing insulin resistance, especially in those with obesity." (PMID 36295825, 2022). "Moreover, high insulin levels and insulin resistance constitute an unfavorable biochemical environment in the ovaries." (PMID 35565885, 2022). "Palmitate induces insulin resistance by enhancing PTP1B expression in insulin target tissues." (PMID 36145191, 2022). "Therefore, the excess weight goes in hand with increased fasting plasma insulin but appears before overt glucose intolerance and insulin resistance in Nkcc1βKO mice." (PMID 36580474, 2022). "Moreover, hyperglycemia in GDM patients is induced by insulin secretion that is inadequate to compensate for the concurrent insulin resistance." (PMID 35432202, 2022). "SPARC expression is markedly up-regulated in AT in obese rodent models and humans with obesity, and is positively correlated with metabolic parameters such as fasting insulin and glucose levels, homeostatic model assessment for insulin resistance (HOMA-IR), waist circumference and hsCRP." (PMID 35909571, 2022). "Abnormalities of insulin signaling are responsible for insulin resistance." (PMID 35455055, 2022). "Moreover, the action of insulin on sodium handling is frequently preserved in insulin resistance and contributes to sodium retention and arterial hypertension." (PMID 34678858, 2022). "Hyperglycemia observed after glucose load in type 2 diabetic humans normally results from both insulin resistance and impaired β-cell function, which is similar to our study where the insulin level is also increased along with glucagon and glucose in the PC group." (PMID 35078449, 2022). "While circulating monocytes and adipose tissue macrophage (ATM) are increased with obesity, the ablation of genes affecting activation or recruitment of myeloid cells could normalize insulin sensitivity in obese insulin resistance animals." (PMID 36569870, 2022). "Additionally, increasing the daily insulin dose leads to an increase in weight, which further worsens insulin resistance." (PMID 35793375, 2022). "The pathological condition of insulin resistance prevents the neuroprotective effects of insulin." (PMID 36589857, 2022). "In addition, we did not have biochemical data such as hormonal profiles, blood glucose levels, hemoglobin A1C concentrations, insulin, C-peptide levels, or calculation of homeostasis model assessment for insulin resistance for evaluating their impacts." (PMID 35585577, 2022). "Also, iron overload and increased oxidative stress leading to inhibition of insulin internalization and function can result to hyperinsulinemia and insulin resistance with high Hb levels." (PMID 35102239, 2022). "Data reported by Thornton and Schultz showed altered glucose metabolism during the administration of a pharmacological dose of nicotinic acid in ruminants, i.e., increased plasma glucose and insulin concentrations as well as reduced glucose tolerance and insulin resistance." (PMID 35739861, 2022).
Insulin resistance (continued). "The relative or absolute lack of insulin in the early stage of insulin resistance and type II diabetes can cause cognitive decline, which share common neuropathological characteristics." (PMID 35800979, 2022). "The beneficial role of Cr(III) supplementation may result from its pharmacological effect, as it increases insulin sensitivity and can alleviate insulin resistance." (PMID 36297315, 2022). "Insulin resistance disrupts hepatic fatty acids flux, reduces muscle fatty acid uptake, and upregulates adipose tissue lipolysis due to resistance to the antilipolytic effects of insulin that can propagate dyslipidemia." (PMID 36520430, 2022). "It has been revealed that 2-AG can act as an insulin resistance biomarker in postmenopausal women and could be used to discriminate the insulin-sensitive obese from insulin-resistant obese phenotypes." (PMID 36329422, 2022). "Overall trajectory data in South Asians were suggestive for a long-term β-cell compensation elicited by a chronic insulin resistance detectable from childhood, and for an inability to produce further insulin to overcome the decreasing insulin sensitivity after the 60 years." (PMID 36614099, 2022). "Furthermore, PLT3-treated mice exhibited significant improvements in glucose intolerance, insulin resistance, and hyperinsulinemia (5 l), suggesting that adipose-targeted delivery of T3 potently enhances insulin sensitivity." (PMID 36539421, 2022). "Conversely, other studies demonstrated that vitamin D was inversely associated with fasting insulin and insulin resistance in the Non-Hispanic Whites and Mexican Americans, but not in the Non-Hispanic Blacks." (PMID 36313112, 2022). "Participants suggested that weaknesses and threats could be mitigated by translating education material into local languages and using the lived experiences of insulin-treated patients to address insulin resistance." (PMID 35924623, 2022). "In the present study, we characterized a muscle cell model of hyperinsulinemia‐induced insulin resistance and establish that the transcriptomic changes in our in vitro model are consistent with those observed in human skeletal muscle across a range of insulin resistant states." (PMID 34921686, 2022). "The fetal insulin hypothesis proposes that genetically determined insulin resistance in the fetus results in impaired insulin-mediated fetal growth as well as insulin resistance in adult life." (PMID 35606578, 2022). "In addition to inducing insulin resistance in insulin-responsive tissues, TNF-α also plays an important role in the pathogenesis of β cell dysfunction." (PMID 35198097, 2022). "Given that nicotine has been shown to reduce insulin sensitivity, this supports the hypothesis that tobacco use, by way of increasing insulin resistance, contributes to the development of LADA." (PMID 35846274, 2022). "Other detailed studies on the mechanism of action of mulberry leaf extract and DNJ in mice suggested that it improved insulin resistance by modulating the insulin signaling pathway in the skeletal muscle of db/db mice after mulberry leaf or DNJ supplementation." (PMID 36558434, 2022). "Therefore, an increase in phosphorylation of IRS1 on serine residues leads to insulin resistance and a decrease in Akt (a downstream molecule in the insulin signaling pathway) phosphorylation." (PMID 36143409, 2022). "Additionally, other beneficial metabolic effects were revealed including a significant reduction in inflammatory markers such as serum insulin, homeostasis model assessment of insulin resistance and serum hs-CRP." (PMID 35546876, 2022). "Consequently, these mice showed a significant impairment in both glucose and insulin tolerance tests under standard diet fed conditions, and an exacerbated peripheral insulin resistance induced by high fat diet." (PMID 35527999, 2022).
Insulin resistance (continued). "Insulin resistance is regulated by multiple factors under physiological conditions, including insulin, insulin receptor (InsR), insulin receptor substrate (IRS), glucose transporter 4 (GLUT4), as well as the Akt, mitogen activated protein kinase (MAPK), and AMPK pathways." (PMID 35330934, 2022). "In addition to an increase in insulin resistance, it was noticed that a short-term statin treatment increases insulin secretion, a well-known compensatory response to increases in insulin resistance." (PMID 36012589, 2022). "Moreover, women requiring larger insulin doses to achieve glycaemic control during pregnancy (a surrogate measure for insulin resistance) had later SA." (PMID 35405936, 2022). "Another phosphatase family member, dual-specificity phosphatase-9 (DUSP-9), also known as MKP4, is also proven to be involved in insulin resistance due to its expression in insulin-sensitive tissues and the modulation of DUSP-9 expression in insulin-resistant states." (PMID 36558920, 2022). "One school of thought is that disturbances in lipid metabolism directly influence insulin signaling, leading to impaired secretion of insulin, which contributes to the development and progression of insulin resistance and abnormal glucose metabolism that leads to T2DM." (PMID 36148775, 2022). "T2D starts with the onset of insulin resistance, which is a cumulative health consequence of obesity, dysfunctional adipose tissue, chronic inflammation, and decrease in pancreatic β-cell mass and consecutive failure in the production of insulin." (PMID 36582536, 2022). "Thus, all of these pro-inflammatory cytokines act in an autocrine and paracrine manner to promote insulin resistance by interfering with insulin signaling in peripheral tissues." (PMID 35276970, 2022). "In women, plasma CNTF showed a moderate correlation with WHR; notably, there was a strong correlation with BMI, the insulin resistance indices fasting insulin and HOMA index and the inflammatory markers hsCRP and IL-6, as well as a very strong correlation with leptin." (PMID 35585213, 2022). "Indeed, P. gingivalis LPS exposure leads to increased secretion of resistin and leptin involved in insulin resistance and decreased secretion of adiponectin recognized as an insulin-sensitizing molecule." (PMID 35327570, 2022). "A HFD profoundly affects several physiological and pathological mechanisms and is a major risk factor for metabolic syndromes such as hypertension, dyslipidaemia, and insulin resistance to diabetes mellitus, and has the ability to reduce sensitivity to insulin." (PMID 36235772, 2022). "Elevated plasma fibrinogen is characteristic of insulin resistance in the liver (the synthesis of fibrinogen may be controlled by insulin)." (PMID 35369595, 2022). "Insulin secretory function compensates for the increase in insulin resistance." (PMID 35831319, 2022). "Glucose tolerance test revealed similar blood glucose levels between the two genotypes, suggesting that pancreatic insulin secretion might be increased to compensate insulin resistance in KO mice." (PMID 35874700, 2022). "The values of alanine aminotransferase (p < 0.001), γ-glutamyl transpeptidase (p < 0.001), uric acid (p = 0.048), fasting plasma glucose (p = 0.01), insulin (p = 0.01), and homeostasis model assessment insulin resistance (p = 0.008) were significantly elevated in the heavy-weight groups." (PMID 35207343, 2022). "Since macrophage function apparently is directly regulated by insulin, it may be assumed that insulin resistance in macrophages also affects their function." (PMID 35955975, 2022). "Looking to the future, deciphering a novel biological mechanism based on the role of the BVR-A protein to identify early alterations of the insulin signaling pathway may have a significant impact on both systemic and brain insulin resistance development." (PMID 35628384, 2022).
Insulin resistance (continued). "Estrogen might regulate insulin through insulin-sensitive tissues or by regulating factors such as oxidative stress that contribute to insulin resistance." (PMID 35209709, 2022). "Chronic insulin treatment resulted in a significant increase in intracellular formation of superoxide anions, hydrogen peroxide, and hydroxyl radicals in 3T3-L1 fat cells, leading to the development of insulin resistance." (PMID 36589440, 2022). "A physical barrier created by enhanced collagen deposition in the endomysium, epimysium, and basement membrane in the muscles may impair glucose uptake and the binding of insulin to its cell surface receptor, leading to insulin resistance." (PMID 36430743, 2022). "Thus, insulin resistance is a pathophysiological condition characterized by a reduced insulin response by peripherical tissues, contributing to hyperglycemia, dyslipidemia, hyperinsulinemia and other alterations." (PMID 35651975, 2022). "Serum thyroid-stimulating hormone (TSH), free triiodothyronine (fT3), free thyroxine (fT4), fasting blood glucose, fasting insulin, homeostatic model assessment method of insulin resistance (HOMA-IR), leptin, and adiponectin levels were estimated in all participants." (PMID 35501770, 2022). "Despite strong evidence linking plasma dihydroceramides to decreased insulin sensitivity, mechanistic studies to determine if circulating dihydroceramides cause insulin resistance are lacking." (PMID 36030929, 2022). "Besides, insulin levels, insulin resistance (HOMA-IR) and inflammatory markers (such as: CRP and IL-6) were not complete for all patients." (PMID 35193565, 2022). "Moreover, there was an increased insulin level observed in the T2DM rats that signified the development of insulin resistance." (PMID 36362316, 2022). "Similarly, β-arrestin 2-KO mice developed insulin-resistance, followed by decreased insulin-induced phosphorylation of Akt, GSK-3β, and FOXO1." (PMID 35430346, 2022). "Moreover, whole body and hepatic insulin resistance with compensatory increased insulin secretion occurred." (PMID 36513656, 2022). "Insulin resistance can be achieved by bizarre insulin affirmation." (PMID 35268815, 2022). "First elevated RBP4 level impairs insulin cascade signaling in muscle and visceral adipose tissue, contributing to the pathogenesis of insulin resistance, and both the incident obesity and type 2 diabetes were the well-established risk factors for CAD and its severity." (PMID 35369314, 2022). "In adults, leptin is positively correlated with fasting insulin concentrations and is a predictor of glucose intolerance, insulin resistance and MetS regardless of underlying obesity." (PMID 35743665, 2022). "Furthermore, it has been shown that the variations in glucose tolerance and insulin resistance are also strain-dependent as they indicated that C57BL/6 mice are more insulin-sensitive than AKR mice." (PMID 35360679, 2022). "A previous study indicated that patients with a high level of insulin Ab may develop severe clinical consequences, such as insulin resistance or hyperglycemia." (PMID 36589820, 2022). "In addition, IL-6 can also induce insulin resistance by reducing insulin sensitivity, or by affecting lipid metabolism." (PMID 35846289, 2022). "The results in our study suggest that IL-10 might counteract the negative effects of adiposity-related cytokines, such as IL-6, on insulin sensitivity, which is corroborated by a study in mice where IL-10 co-treatment prevented IL-6 induced insulin resistance." (PMID 35135482, 2022). "Sclerostin levels are strongly correlated with plasma insulin and insulin resistance." (PMID 35742035, 2022). "On the other hand, there are clear examples of true insulin resistance both in the periphery and CNS, defined by the blunted action of insulin on the IR signaling pathway, most commonly measured by phosphorylation events following insulin stimulation." (PMID 35884888, 2022).
Insulin resistance (continued). "Stimulation of insulin signaling pathways through the solute carrier family 2 (facilitated glucose transporter) members 4 and 2 was the mechanism underlying the beneficial effects of EEI on obesity-induced insulin resistance." (PMID 36432581, 2022). "Abnormal insulin signaling pathway, as a common pathogenic mechanism in T2DM and HF, could lead to pathological features such as insulin resistance (IR), myocardial energy metabolism disorders, and vascular endothelial disorders." (PMID 35308248, 2022). "Hence, drugs to promote the proliferation of β cells, increase insulin secretion, and improve insulin resistance have been extensively investigated." (PMID 36295827, 2022). "In addition, we observed a more rapid relief of insulin resistance (WBISI increased 5.22-fold) than glucose induced insulin secretion (IGI only reduced by 1.8%)." (PMID 36407309, 2022). "Insulin resistance is characterized by a higher insulin level in the periphery, which will inhibit the reuptake of CAs and activate adrenergic receptors on α and β cells constantly, resulting in damage to glucose homeostasis and accelerating the progression to T2D." (PMID 35669692, 2022). "In addition, the HOMA-IR index was also used in the present study, which is a common indicator to evaluate insulin sensitivity, insulin resistance and pancreatic β-cell function in diabetic patients." (PMID 36358563, 2022). "Insulin resistance could contribute to this diminished cellular immunity in T2D, as insulin administration decreases infection and complication rates in T2D populations." (PMID 36013497, 2022). "Evaluating pre and post values, Hesperidin was able to reduce the serum levels of glucose (p < 0.001), insulin (p < 0.001), the homeostasis model assessment of insulin resistance (HOMA-IR) (−0.70, p < 0.001) TG (p = 0.002), TC (p < 0.001), LDL-c (p = 0.010), TNF-α (p < 0.001) and hs-CRP (p = 0.008)." (PMID 35955475, 2022). "Consequently, altered insulin action in skeletal muscle can lead to a pathological state of insulin resistance, in which normal concentrations of insulin induce an impaired biological response." (PMID 35185804, 2022). "However, the beneficial effects of insulin that predominate under normal conditions are reversed in the face of insulin resistance and hyperinsulinemia." (PMID 36160146, 2022). "Lean patients with type 2 diabetes may have a tendency toward certain pathophysiological characteristics, notably less insulin resistance and poorer insulin secretory capacity." (PMID 35351050, 2022). "Exploring the regulatory roles of EVs in the development and progression of insulin resistance can not only help us understand the mechanisms for blocking the transmission of insulin signaling but also provide us with potentially effective EV-based preventive and therapeutic strategies." (PMID 36699697, 2022). "Meanwhile, long-term and repeated nocturnal hypoxic stress responses may increase the antagonistic products of insulin in the body, thereby aggravating insulin resistance." (PMID 36120463, 2022). "As expected, we have noticed that HFD induced whole body insulin resistance, as evidenced by increased levels of both, fasting glucose and insulin, impaired glucose and insulin tolerance, as well as increased HOMA-IR index as compared to animals fed the standard low-fat diet." (PMID 35053322, 2022). "Additionally, the subjects with insulin resistance show altered insulin brain regulation with reduced valuation to food cues in the VTA and nucleus accumbens." (PMID 35276920, 2022). "Insulin in diabetic patients loses its function of promoting cellular glucose uptake and utilization, leading to insulin resistance, which destroys the role of insulin in inhibiting muscle protein breakdown, resulting in muscle fiber atrophy, muscle mass reduction and muscle strength decline." (PMID 36584211, 2022).